EPO (erythropoietin)
Diseases named in the same sentence as EPO in open-access papers (continued):
Sharing a sentence is not in itself a finding about the gene and the disease.
hematoma (1 paper, 2018). A hematoma is a collection of blood from a vascular structure into an extravascular space. "Our findings are in line with previous observation showing that EPO-mediated increase in expression around hematoma helps in reducing brain swelling." (PMID 29982881, 2018).
Hepatic hemangioma (1 paper, 2016). A congenital vascular malformation in the liver composed of masses of blood vessels that are atypical or irregular in arrangement and size. "In short, we found that LRRK2 could affect EPO expression in the kidneys and livers of aged mice, which might be related to the formation of hepatic hemangiomas." (PMID 27872856, 2016).
histoplasmosis (1 paper, 2015). A disease caused by the fungus Histoplasma capsulatum. "Considering that macrophages and lipid mediators are important for the control of Hc infection and that EPO might act on these two parameters, our aim was to investigate the effects of EPO pretreatment on experimental histoplasmosis." (PMID 26538835, 2015).
HIV-1 infection (1 paper, 2024). The type species of lentivirus and the etiologic agent of acquired immunodeficiency syndrome (AIDS). "HIV-1 infection of T cells and HSCs activates the NF-κB dependent pathway, resulting in impaired hematopoiesis, the production of inflammatory cytokines that further exacerbate and downregulate EPO production." (PMID 38675885, 2024).
hypertrophic cardiomyopathy (1 paper, 2024). A condition in which the myocardium is hypertrophied without an obvious cause. "ΔEPORE mice also showed an increased systolic volume and systolic diameter compared to WT male mice, suggesting that in WT mice, endogenous EPO in non-hematopoietic tissues might play a role in protecting against hypertrophic cardiomyopathy." (PMID 38628440, 2024).
Hyponatremia (1 paper, 2024). An abnormally decreased sodium concentration in the blood. "SGLT2is can modulate non-osmotic sodium storage, decreasing the skin’s sodium content and interstitial fluid volume and improving dilutional hyponatremia by increasing erythropoietin production and hematocrit." (PMID 39590207, 2024).
hypophosphatemia (1 paper, 2017). Lower than normal levels of phosphates in the circulating blood. "The occurrence of hypophosphatemia in dialysis patients is caused by avoidance of phosphate-containing food (milk, meat, fish, eggs, etc.), malnourishment, parenteral nutrition, and use of medications such as phosphate-binding antacids or erythropoietin." (PMID 28973026, 2017). "Generally, it is rare for decreased intake alone to cause hypophosphatemia, but malabsorption and use of specific drugs, such as phosphate-binding antacids or erythropoietin, can decrease intestinal phosphate absorption or shift phosphate from the extracellular space into the cell." (PMID 28973026, 2017).
hypoplastic left heart syndrome (1 paper, 2018). Hypoplastic left heart syndrome (HLHS) refers to the abnormal development of the left-sided cardiac structures, resulting in obstruction to blood flow from the left ventricular outflow tract. "Fifty-nine neonates (age < 30 days) with TGA, hypoplastic left heart syndrome (HLHS) or aortic arch anomalies received 3 intravenous doses of EPO (500 or 1,000 U/kg) or placebo before and after hypothermic CPB." (PMID 30018590, 2018).
hypoxia (1 paper, 2017). A decrease in the amount of oxygen in the body. "Intranasal rHu-EPO was able to recover spontaneous motor activity, without induction of peripheral erythropoiesis in a focal brain hypoxia model." (PMID 28676085, 2017).
infectious diseases of the central nervous system (1 paper, 2012). "Although EPO exerts protective effects in non-infectious diseases of the central nervous system, the outcome of E. coli-meningitis is not influenced by EPO treatment." (PMID 22094132, 2012).
interstitial nephritis (1 paper, 2025). Inflammation of the renal tubules and supporting tissues of the kidney. "Therefore, it could be speculated that hemoglobin and EPO levels might have a U-shaped pattern in interstitial nephritis according to the degree of interstitial inflammatory cell infiltration." (PMID 39190047, 2025).
invasive breast carcinoma (1 paper, 2017). A carcinoma that infiltrates the breast parenchyma. "In particular, quantification of the expression of EPO, ETS1, PGK1, TPI, LDHA and ENO1 in a primary tumor sample provides information on the risk of recurrence for patients with early-stage invasive breast cancer." (PMID 28430808, 2017).
keratinocyte carcinoma (1 paper, 2023). A skin cancer arising from the keratin-producing cells of the epidermis. "Using whole exome sequencing data, we performed groupwise tests for rare missense variants in our dataset and found robust associations (p < 10−6, Burden Zeggini test) between MC1R, EPHA8, EPO, MYCT1, ADGRG3, and MGME1 and keratinocyte cancer." (PMID 37444464, 2023).
kidney stones (1 paper, 2018). "However, patients with kidney stones have erythropoietin resistance caused by bone marrow oxalosis." (PMID 29530009, 2018).
liver failure (1 paper, 2010). A liver disease characterized by the liver losing or has lost all of its function. "This can be added to the apparent beneficial effect of EPO in reducing blood transfusions that are associated with increased morbidity and might be of particular clinical interest in situations where hepatectomy is expected to result in significant liver failure and increased mortality." (PMID 20604971, 2010).
lymphoid tumours (1 paper, 2003). "In this study, in patients with lymphoid tumours, 52% of patients with a serum erythropoietin O/P ratio <0.9 achieved the expected response to therapy (Hb increase ⩾2 g dl−1), compared with 27% of patients with a baseline O/P ratio ⩾0.9." (PMID 12671693, 2003).
lysinuric protein intolerance (1 paper, 2025). Lysinuric protein intolerance (LPI) is a very rare inherited multisystem condition caused by disturbance in amino acid metabolism. "The hematopoietic defects in the Lysinuric protein intolerance mouse model are not caused by intrinsic Slc7a7 loss in hematopoietic cells but rather by impaired erythropoietin production in the kidney." (PMID 39881295, 2025).
Macrocephaly (1 paper, 2018). Occipitofrontal (head) circumference greater than 97th centile compared to appropriate, age matched, sex-matched normal standards. "In addition to preventing macrocephaly, neonatal EPO+MLT treatment also mitigated poor performance on cliff aversion after CAM-IVH." (PMID 30319361, 2018). "Moreover, while we demonstrated that both sexes develop progressive macrocephaly, the study was not sufficiently powered to determine how well each sex responds to EPO+MLT treatment." (PMID 30319361, 2018).
male infertility (1 paper, 2024). The inability of the male to effect fertilization of an ovum after a specified period of unprotected intercourse. "Further research is needed to investigate the efficacy of EPO in protecting the quality of cryopreserved sperm and to determine which molecular pathways/ligands and genes EPO activates for a better understanding of its role in the fertilization process and male infertility." (PMID 39123702, 2024).
megakaryoblastic leukemia (1 paper, 2020). "UT-7/EPO is a subclone of a UT-7 megakaryoblastic leukemia cell line that was maintained in the presence of EPO for more than 6 months to increase erythroid differentiation." (PMID 32625106, 2020).
megakaryocytic leukemia (1 paper, 2019). "UT7/Epo-S1 is a subline derived from UT7/Epo, which is an erythropoietin (Epo)-dependent cell line, and originating from UT7, a megakaryocytic leukemia cell line." (PMID 31487941, 2019).
memory (1 paper, 2022). The activities involved in the mental information processing system that receives (registers), modifies, stores, and retrieves informational stimuli. "EPO treatment seemed to prevent memory deficit until the last examination, on D33, with the preservation of lengthened step-through latency (p < 0.001)." (PMID 35897720, 2022).
metanephric adenoma (1 paper, 2013). A benign, well-circumscribed renal cortical neoplasm affecting females more often than males. "Tissue cultured from a metanephric adenoma was found to produce significantly elevated concentrations of erythropoietin." (PMID 24171133, 2013).
morbid obesity (1 paper, 2024). An excess of body weight, normally defined as an individual with a body mass index greater than 35 or a body weight greater than one hundred percent of ideal body weight. "It was found that EPO levels were higher in morbid obesity and correlated with higher basal weight, fat mass (FM) and fat-free mass (FFM) in the overall sample." (PMID 38696124, 2024).
Myelopathy (1 paper, 2019). Myelopathy is an descriptive term, referring to pathology leading to a neurologic deficit related to the spinal cord. "The present study demonstrated that EPO improved locomotor functions and preserved motor neurons and axons, even in developing myelopathy due to spinal cord compression." (PMID 31821342, 2019). "On the other hand, the mechanism of neuroprotective effect of EPO for compression myelopathy remains unknown." (PMID 31821342, 2019). "Based on these data, EPO may be a clinically acceptable agent for progressive compressive myelopathy as well as a hematopoietic cytokine." (PMID 31821342, 2019).
myelosuppression (1 paper, 2024). Myelosuppression or bone marrow suppression is a condition in which bone marrow activity is decreased, resulting in fewer red blood cells, white blood cells, and platelets. "A variety of aminothiol small molecules and HGFs, specifically G‐CSF, GM‐CSF, and EPO, have the ability to alleviate radiation‐induced myelosuppression." (PMID 39268354, 2024).
myocarditis (1 paper, 2012). Myocarditis is a condition that is characterized by inflammation of the heart muscle (myocardium). "In previous reports in a rodent model of myocarditis, EPO treatment produced substantial reductions in macrophage infiltration and necrosis while rescuing cardiac function when administered soon after the onset of autoimmune pathology." (PMID 22863174, 2012).
myoma (1 paper, 2018). "With the assumption that hemoglobin and erythropoietin levels would remain low following myoma removal, we chose to proceed with the surgery, rather than repeat phlebotomy." (PMID 32025892, 2018).
nosocomial infection (1 paper, 2023). An infection acquired in a hospital or other healthcare setting. "In orthopedic surgeries, treatment with intravenous iron and subcutaneous erythropoietin 1 to 3 days before surgery was associated with a reduction in the rate of packed red-blood-cell transfusions from 37% to 24%, and nosocomial infections from 12% to 8%." (PMID 36900120, 2023).
oesophageal cancers (1 paper, 2018). "Some studies have shown that in patients with oesophageal cancers, adminstration of erythropoietin led to lower transfusion requirements and a greater survival benefit than placebo." (PMID 29661211, 2018).
of the CNS (1 paper, 2017). "EPOR is expressed in OLs in physiologic conditions, and its levels are increased by hypoxia, injury, and chronic disease, suggesting the involvement of the EPO–EPOR pathway in remyelination upon injury and disease of the CNS." (PMID 29123527, 2017).
oncocytomas (1 paper, 2014). "Expression of EPO within the tumor tissue of RCC is more frequent in clear cell type RCC and has rarely been reported in oncocytomas." (PMID 24520308, 2014).
optic atrophy (1 paper, 2026). A disorder characterized by loss of optic nerve fibers. "We found no clinically meaningful or statistically significant differences between erythropoietin and placebo recipients in terms of lesion changes or optic atrophy." (PMID 42004010, 2026).
pancreatic ductal carcinoma (1 paper, 2023). "Cleavage of erythropoietin-producing hepatocellular ephrin receptor A2 (EphA2) triggers malignant progression and yields an N-terminal fragment (EphA2-NF) detectable in sera from patients with pancreatic ductal carcinoma." (PMID 37712876, 2023).
pancreatitis (1 paper, 2014). Inflammation of the pancreas. "The data show that EPO administration can alleviate pulmonary injury parameters in pancreatitis." (PMID 24761770, 2014).
placental insufficiency (1 paper, 2024). Failure of the placenta to deliver an adequate supply of nutrients and oxygen to the fetus. "This would be in agreement with our observation of significantly different connections between EPO and IL-10 in infants with BW-SDS above or below median, based on the assumption that lower BW-SDS is associated with placental insufficiency and hypoxia." (PMID 39529072, 2024).
plasma cell neoplasm (1 paper, 2016). A clonal proliferation of immunoglobulin-secreting plasma cells. "To examine whether EPO mRNA expression was a specific trait of malignant plasma cells, we used publicly available data sets to compare expression in plasma cells from healthy people and from patients with various stages of plasma cell neoplasms." (PMID 27581518, 2016).
pneumonitis (1 paper, 2024). An inflammatory process affecting the lung parenchyma. "In the CNT SAL and CNT SAL/EPO groups, apart from very mild pneumonitis—as expected after the endotracheal saline—no other damage was observed, and histological preparations were similar to those in the CNT group." (PMID 39338226, 2024).
postnatal depression (1 paper, 2012). "Two reviews showed that women receiving erythropoietin were more likely to be lactating on discharge (two RCTs), with a decrease in postnatal depression scores in the erythropoietin treatment arm." (PMID 22727258, 2012).
presbycusis (1 paper, 2024). Bilateral hearing loss caused by progressive degeneration of cochlear structures and central auditory pathways, typically associated with the aging process. "Therefore, it has been suggested that EPO can effectively suppress the loss of spiral ganglion cells and probably hair cells and, thereby, the development of presbycusis in mice." (PMID 38333758, 2024).
primary hyperparathyroidism (1 paper, 2025). "In endocrine pathologies such as primary hyperparathyroidism (PHPT), EPO resistance is mediated by elevated fibroblast growth factor 23 (FGF23), a hormone implicated in phosphate homeostasis, inflammation, and erythropoiesis." (PMID 41012526, 2025).
Primrose syndrome (1 paper, 2026). "Due to our previous observation of enhanced ZBTB20 expression in CA1 pyramidal neurons upon recombinant human erythropoietin (rhEPO) injections, we anticipated a mitigating effect through rhEPO treatment of Zbtb20 deficiency/Primrose syndrome." (PMID 41729076, 2026).
protein deficiency (1 paper, 2019). "In this study, the low protein content of the turkey berry coupled with protein deficiency in the rats may have reduced erythropoietin production resulting in low Hb." (PMID 31623146, 2019).
renal adenoma (1 paper, 2016). An adenoma arising from the renal cortex. "This may be associated with the renal adenoma cells that produce and secret erythropoietin and a variety of other cytokines." (PMID 27398273, 2016).
renal atherosclerosis (1 paper, 2015). "Inflammation also influences EPO efficacy and production as well as renal atherosclerosis." (PMID 25884723, 2015).
respiratory depression (1 paper, 2021). A decrease in ventilation secondary to impaired signals from the central nervous system. "Proof-of-concept experiments show that the administration of an EPO antagonist (soluble EPO – sEPO) leads to respiratory depression in normoxia, and to asphyxia and increased mortality in hypoxia." (PMID 34987412, 2021). "“Ex-vivo” studies using a brainstem-spinal cord preparation from newborn rodents show that EPO stimulates respiratory rhythm and prevents hypoxia-induced respiratory depression." (PMID 34987412, 2021).
Respiratory distress (1 paper, 2022). Respiratory distress is objectively observable as the physical or emotional consequences from the experience of dyspnea. "In this cohort study of 941 infants enrolled in the Preterm Erythropoietin Neuroprotection Trial, mortality was lower and infants lived longer than in previous decades, and the most common cause of death was respiratory distress or failure." (PMID 35129596, 2022).
respiratory distress syndrome (1 paper, 2020). "In a case study, recombinant human erythropoietin (rhEPO) was suggested to attenuate respiratory distress syndrome by enhancing leukocyte release from bone marrow and iron redistribution away from the intracellular virus." (PMID 33363185, 2020).
respiratory infections (1 paper, 2021). "Thus, respiratory infections were positively associated with age and the need for higher erythropoietin dosages." (PMID 34268290, 2021).
retinal detachment (1 paper, 2009). An eye emergency condition which may lead to blindness if left untreated. "In a mouse-model of retinal detachment, in which photoreceptors die from ischemia, Xie and colleagues demonstrated that there is upregulation of the EPO-EPOR system." (PMID 19930719, 2009).
retinoblastoma (1 paper, 2018). A malignant tumor that originates in the nuclear layer of the retina. "Cellular recovery of human retinoblastoma (Y79) subjected to glutamate at a toxic dose was assessed following incubation with supernatants harvested from EPO-transduced MSCs." (PMID 30108483, 2018). "In this study, we aimed to genetically modify MSCs to produce and secrete human EPO protein and to demonstrate the high potential of dual combination of EPO delivered by MSCs to protect retinal neurons from apoptosis in a glutamate-induced human retinoblastoma (Y79) in vitro model." (PMID 30108483, 2018).
Right ventricular hypertrophy (1 paper, 2018). In this case the right ventricle is more muscular than normal, causing a characteristic boot-shaped (coeur-en-sabot) appearance as seen on anterior- posterior chest x-rays. "However, H2 inhalation in our mouse model of H/R-induced injury did not influence the EPO-red blood cell system, nor did it significantly affect pulmonary artery remodeling or right ventricular hypertrophy." (PMID 29789753, 2018).
scleroderma (1 paper, 2010). Scleroderma is a rare autoimmune connective tissue disorder characterized by abnormal hardening of the skin and, sometimes, other organs. "The erythropoietin analogues are increasingly recognized as stimulators of angiogenesis pathways, and therefore these pathways may merit further investigation in scleroderma." (PMID 20827313, 2010).
skin melanoma (1 paper, 2014). "For skin melanoma, somatic mutations in four genes were significantly enriched in their protein pocket regions, including CRP (P = 2.2 × 10-6), NCF1 (P = 6.3 × 10-4), EPO (P = 2.2 × 10-3), and RWDD1 (P = 2.2 × 10-3)." (PMID 25360158, 2014).
sleep disorder (1 paper, 2023). A change from the patient's baseline sleeping pattern, in the hours slept and/or an alteration/dysfunction in the stages of sleep. "A recent study explored the potential use of EPO levels as a paediatric sleep disorders marker." (PMID 37628330, 2023).
spinocerebellar ataxia (1 paper, 2023). "The proportion of high responders in the spinocerebellar ataxia functional index (SCAFI ≥ 0.75), which is a composite score of motor performances, was slightly higher among the EPO-treated patients than those given a placebo despite a considerable placebo effect." (PMID 37376074, 2023).
spinocerebellar ataxia type 2 (1 paper, 2023). A subtype of type I autosomal dominant cerebellar ataxia (ADCA type I) characterized by truncal ataxia, dysarthria, slowed saccades and less commonly ophthalmoparesis and chorea. "Indirect evidence of neuroEPO plus in the cerebral spinal fluid (CSF) is supported by studies measuring total EPO in the CSF of non-human primates and in patients with Spinocerebellar ataxia type 2 (SCA2)." (PMID 38093366, 2023).